INS (insulin)
Diseases named in the same sentence as INS in open-access papers (continued):
Sharing a sentence is not in itself a finding about the gene and the disease.
diabetes (continued). "Because vitamin D affects insulin secretion and insulin sensitivity, which are important factors in the development of diabetes mellitus (DM), it is possible that vitamin D levels are linked to the development of DM." (PMID 35209709, 2022). "Diabetes mellitus is a chronic metabolic disease caused by absolutely or relatively insufficient insulin secretion and certain degrees of insulin resistance." (PMID 36140883, 2022). "Compared with other intensive therapies (insulin or SU), metformin performed better for any diabetes-related endpoint, all-cause mortality and stroke." (PMID 35337110, 2022). "A beneficial effect of weight loss on insulin sensitivity and diabetes prevalence is well established, in general." (PMID 35897098, 2022). "Human rare LOF mutations of ZnT8 decrease the risk of diabetes and improve insulin secretion from pancreatic β cells." (PMID 35842441, 2022). "The various miRNAs in exosomes associated with diabetes mellitus include miR-142-3p, miR-142-5p, and miR-155 from lymphocytes that can cause selective death of insulin-secreting beta cells." (PMID 36726968, 2022). "Given the current results, we cannot, however, exclude that other diabetes-associated factors, such as obesity or impaired insulin signaling, contribute to a plaque instability in diabetic patients." (PMID 35889743, 2022). "A hallmark of the early stages in diabetes is the disruption of the first-phase peak of insulin secretion." (PMID 36099294, 2022). "Nutrients, especially glucose and glutamine, influence the insulin secretion of pancreatic-β cells, and their imbalance is associated with diabetes and diabetes-related complications." (PMID 35672290, 2022). "They isolated and purified insulin from the pancreas of cattle from slaughterhouses with the goal of using it to treat human insulin-deficient juvenile (type 1) diabetes mellitus." (PMID 35921488, 2022). "The metabolic disorder known as diabetes mellitus (DM) has several different causes, distinguished by recurring hyperglycemia due to inadequate insulin secretion, insulin action, or both." (PMID 36312660, 2022). "Type 2 diabetes mellitus (T2DM) is a chronic metabolic disease caused by reduced insulin sensitivity of tissue cells and insufficiency of insulin secretion." (PMID 35267387, 2022). "Our in vitro studies conducted in pancreatic islet culture, have shown that certain types of bacteria and fungi can directly cause increased or decreased insulin secretion of the pancreas leading to insulin resistance and the development of diabetes mellitus." (PMID 36397429, 2022). "In our study, remission was associated with lower HbA1c and lower daily insulin requirements during the 5 first years of diabetes diagnosis." (PMID 35315990, 2022). "Fetuin-A (Fet-A) is a liver-secreted phosphorylated protein, known to impair insulin signaling, which has been shown to be associated with obesity, insulin resistance, and incident diabetes." (PMID 35522655, 2022). "Lower age at diabetes diagnosis, rural residence, shorter duration of diabetes, presence of any diabetic complication, insulin use, and presence of major were the risk factors for DD observed in this study." (PMID 35065623, 2022). "Increased GIP release leads to increased insulin secretion that causes insulin insensitivity and type 2 diabetes mellitus (T2DM)." (PMID 35224107, 2022). "Results from five studies (11 articles) that investigated associations with blood glucose, insulin or diabetes outcomes (collectively ‘metabolic outcomes’) were included in the synthesis, covering four exposures, with participants aged 5–34 years." (PMID 35954531, 2022). "It has also been reported that TNF-α is associated with the development of diabetes and can also alter insulin-mediated glucose uptake in muscle cells in vitro." (PMID 36060470, 2022).
diabetes (continued). "People with diabetes are at risk of hypoglycaemia in the 24 hours after exercise due to the increased glucose disposal needed to replenish glycogen stores and increased insulin sensitivity." (PMID 36425473, 2022). "People with diabetes are at higher risk for diabetes-related complications and death if they cannot access insulin, even for short intervals." (PMID 35436214, 2022). "Loss of GLIS3 results in a drastic reduction in insulin expression, leading to hyperglycemia that subsequently induces beta-cell apoptosis and culminates in severe fulminant diabetes.." (PMID 35246208, 2022). "The failure of insulin to suppress lipolysis in adipocytes has been long considered as a crucial risk factor for the development of IR and diabetes mellitus." (PMID 35283787, 2022). "Research indicates that diet composition can be manipulated to improve insulin sensitivity and reduce the risk of diabetes." (PMID 35267895, 2022). "Aberrant glucagon secretion and signaling is a hallmark of both type 2 (insulin resistant) and type 1 (insulin deficient) diabetes." (PMID 36002172, 2022). "It is generally believed that diabetes was a severe disease, and if uncontrolled, diabetics were at risk of severe complications or required insulin injection." (PMID 36263317, 2022). "The present studies are the first to explore effects of drug treatments other than insulin on diabetes-associated bladder enlargement." (PMID 36003651, 2022). "Diabetes is a group of metabolic diseases characterized by hyperglycemia caused by defects in insulin secretion or its action." (PMID 35846887, 2022). "Associations between insulin use and comorbidities remained the same after accounting for diabetes knowledge and self-care." (PMID 36340524, 2022). "In humans, diabetes mellitus, which is caused by defects in insulin signaling, is associated with mood disorders that affect daily behavioral activities." (PMID 35729173, 2022). "Among the clinical factors, insulin dose, diabetes duration, and proteinuria were associated with the risk of hypoglycemia positively; meanwhile, HbA1c, eGFR, and BMI demonstrated negative associations." (PMID 36013211, 2022). "Diabetes patients have insulin signal transduction pathway changes or defects, which are associated with lower levels of the molecules of insulin signaling such as “Insulin receptor substrate-1 (IRS-1) and phosphatidylinositol 3-kinase PI3K”." (PMID 36160451, 2022). "Diabetes mellitus (DM) is a worldwide chronic disease characterized by hyperglycemia and neurovascular damages caused by insulin deficiency or insulin insensitivity." (PMID 35510503, 2022). "Insulin treatment during pregnancy and subsequent development of manifest diabetes exacerbated the risk estimates." (PMID 36085031, 2022). "Diabetes is a group of metabolic diseases caused by decreased insulin secretion, insensitivity to insulin action of the body, or both, with a chronic increase of blood glucose level and multiple chronic complications as the main clinical features." (PMID 35356504, 2022). "In the 1920s, before the discovery of insulin and antibiotics, the main causes of death among patients with diabetes were ketoacidosis and infectious diseases." (PMID 35629125, 2022). "ATP6AP2 deficiency is the exacerbated generation and accumulation of multigranular bodies that consume the cytoplasm of beta cells, ensnaring insulin secretory granules (SGs) and thus causing insulin-deficient diabetes." (PMID 35885938, 2022). "Nanomaterial‐assisted biomedicine has shown significant advantages in almost all kinds of diabetes‐associated diagnosis and therapy, i.e., diabetic biomarker detection, glucose control, insulin mimicking, and prevention of complications." (PMID 34825525, 2022). "It is notable that insulin has been demonstrated to have a biological effect on corneal epithelialization, and diabetes mellitus is a recognized cause of neurotrophic keratitis." (PMID 35392574, 2022).
diabetes (continued). "Overproduction of growth hormone has been associated with diabetes and metabolic disease for decades and the opposing effects of growth hormone and insulin have been studied since early experiments almost a century ago." (PMID 35474620, 2022). "Studies in humans have shown that 1.5 g of GlcN fed orally for 6 weeks augmented the risk for diabetes in adults with previous poor insulin sensitivity." (PMID 36124412, 2022). "In this study, EEAS was found to decrease insulin glycation in vitro, indicating its potential against insulin resistance and diabetes-associated complications." (PMID 36295897, 2022). "Clinical studies illustrated how circadian misalignment and sleep restriction were correlated with changes in glucose tolerance and insulin sensitivity, and therefore with a higher risk of developing diabetes and metabolic syndrome." (PMID 35406023, 2022). "Recurrent iatrogenic hypoglycemia leading to hypoglycaemia associated autonomic failure is a serious complication in insulin-treated diabetes and is a limiting factor in maintaining proper glycemic control." (PMID 35207609, 2022). "Conclusive detrimental associations with sedentary behaviour were determined for 2-h insulin (6/12 studies found associations), fasting insulin (15/19 studies), insulin sensitivity (4/6 studies), diabetes (3/4 studies) and IL-6 (2/3 studies)." (PMID 35544519, 2022). "Diabetes causes glucose, lipid, and protein metabolism irregularities due to insulin’s ineffective activity on target tissues." (PMID 35956419, 2022). "The SHD cluster was specific to the current study and is likely to include the previously reported ‘severe insulin deficient diabetes’ and ‘severe insulin resistant diabetes’ clusters." (PMID 35577589, 2022). "The tissue-specificity analysis further revealed the enrichment of associated genes in the pancreas, a key organ in diabetes mellitus as pancreatic β-cells are responsible for insulin biosynthesis and secretion." (PMID 36620623, 2022). "T2DM results from insulin resistance and a progressive loss of sufficient β-cell insulin production." (PMID 36467726, 2022). "All these benefits behind CM intake allow it to play a role in mitigating the risk of diabetic complications among patients with diabetes and the side effects for the long-term excessive use of insulin injections." (PMID 35334901, 2022). "The American Diabetes Association has also made a positive recommendation for adding MET to insulin therapy in overweight patients with T1DM." (PMID 36327331, 2022). "Compared to metformin, diabetes treatment with insulin or insulin secretagogues has a higher risk of getting cancer." (PMID 35408706, 2022). "Previously reported risk factors for falls among those with diabetes include diabetic polyneuropathy, diabetic retinopathy, increased cystatin C levels and insulin or sulfonylurea use as well as decreased grip, knee extension and ankle dorsiflexion strength." (PMID 35831378, 2022). "Diabetes is a metabolic disease characterized by hyperglycemia, which is caused by defective insulin secretion or impaired function." (PMID 36291040, 2022). "Type 2 diabetes mellitus (T2DM) is the most common type of diabetes worldwide; it occurs due to insulin resistance and gradual loss of β-cells functions of the pancreas." (PMID 35646179, 2022). "Loss of function and/or cell mass of insulin-producing β-cells of the pancreatic islets leads to pancreatogenic diabetes mellitus (DM), also termed type 3c DM7,8." (PMID 36515672, 2022). "Although reducing insulin resistance is beneficial in people with diabetes, it also bears the risk of hypoglycaemia in people treated with insulin." (PMID 35179802, 2022). "Glucocorticoids affect several insulin-signaling pathways, leading to reduced insulin sensitivity, inducing insulin resistance, and increasing the risk of diabetes." (PMID 35406580, 2022).
diabetes (continued). "Their study demonstrated the genetic susceptibility of women with a history of GDM to impaired insulin secretion and sensitivity, and consequently to the development of diabetes." (PMID 36009479, 2022). "Diabetes is caused by an absolute deficiency in insulin secretion (type 1) or a combination of insulin resistance and insulin secretory defect (type 2), and affects millions of people around the world." (PMID 35804780, 2022). "Almost all metabolites, including glucose and insulin, returned to baseline values at the end of the test (at 240 min), except a variety of amino acids and here those that have been linked to diabetes development." (PMID 35774538, 2022). "Diabetes mellitus (DM) can develop after RT as it can cause late parenchymal structural damage to the pancreas, resulting in a significant decrease in insulin secretion that is associated with glucose intolerance." (PMID 36077647, 2022). "Type 1 diabetes mellitus (T1DM) is characterized by deficient insulin production and requires daily administration of insulin." (PMID 35656460, 2022). "Type 1 diabetes mellitus (T1DM) is caused by insufficient insulin secretion, and T2DM results from insulin resistance." (PMID 35422764, 2022). "Poor insulin signaling, insulin resistance, and oxidative stress condition caused by diabetes contribute to neuronal degeneration, leading to memory loss." (PMID 35328405, 2022). "Relative or absolute deficiency of insulin secretion and insulin action is the basic pathogenesis of diabetes." (PMID 36157449, 2022). "STZ is the most widely used chemical drug for establishing the diabetes mice or rat model, which causes pancreatic islet damage and thus reduces insulin secretion." (PMID 36364880, 2022). "Diabetes mellitus (DM) is associated with a reduction in insulin production or relative changes that increase glucose levels in the blood during insulin activity." (PMID 35055148, 2022). "Excluding individuals with probable type 1 diabetes who were diagnosed as diabetes before 20 years of age and treated with only insulin, a robust relationship between serum Hcy and mortality risk was still identified." (PMID 36267812, 2022). "Insulin can be initiated at a dose of 0.1–0.2 units/kg/day and titrated based on clinical response according to the American Diabetes Association guidelines." (PMID 35016012, 2022). "Diabetes is characterized by elevated blood glucose levels caused by insufficient insulin production or insufficient insulin activity (Blüher, 2013)." (PMID 36620773, 2022). "The leading causes of diabetes are the pancreas being unable to produce enough insulin (juvenile diabetes) or when the body becomes resistant to insulin (adult-onset diabetes)." (PMID 36558993, 2022). "The existing literature suggests that increased lymphocyte counts are associated with decreased insulin sensitivity and higher risk to develop diabetes." (PMID 35154341, 2022). "The known risk factors for hypoglycemia are the duration of diabetes, history of previous severe hypoglycemia, hypoglycemia unawareness, change in insulin treatment, and HbA1c <6.0% (42 mmol/mol)." (PMID 35207323, 2022). "Diabetes is a risk factor for liver cancer development and is commonly characterized by abnormally high glucagon signaling, likely as a result of decreased insulin sensitivity." (PMID 35123542, 2022). "Chronic high glucose induce β-cell membrane hyperexcitability, persistently elevated intracellular calcium concentration and insulin hypersecretion, all critically contributing to loss of β-cell mass in diabetes." (PMID 35180212, 2022). "Loss of memory in diabetes mellitus because of dysregulated glucose–insulin balance has been demonstrated." (PMID 37551286, 2022). "Chronic hyperglycemia is the main characteristic of diabetes mellitus (DM), which is caused by decreased insulin action or secretion or both." (PMID 35888760, 2022).
diabetes (continued). "IL-1β and IL-18 have different roles in diabetes, with IL-1β contributing to type 2 diabetes by attenuating the insulin secretion function of β-cells, and IL-18 being associated with type 1 diabetes." (PMID 36232938, 2022). "SORSC1 has been associated with insulin secretion and diabetes risk and loss of both Sorcs1 and Sorcs3 in mutant mice caused increased adiposity and enhanced food intake, but not increased body weight." (PMID 35330733, 2022). "For example, increasing evidence demonstrates that death of pancreatic B cells is the main cause of insufficient insulin secretion in diabetes." (PMID 35422764, 2022). "Findings suggest that ARAP1 engages in islet insulin content and secretion and is thus likely to mediate the effects on diabetes susceptibility." (PMID 35399945, 2022). "Interleukin 6 (IL6) and tumor necrosis factor (TNF) are conventional pro-inflammatory cytokines believed to be risk factors for diabetes progression due to their disturbance of insulin signaling." (PMID 36432581, 2022). "Type 2 diabetes comprises most patients with diabetes, which is caused by inefficiency of insulin and is related mainly to environmental factors like dietary intake and physical inactivity." (PMID 35769727, 2022). "T1DM accounts for the remaining 10% of diabetes cases and is caused by the immune-mediated T-cell attack on insulin-producing β-cells in the pancreatic islets." (PMID 35324794, 2022). "As a continuous metabolic disease, type 2 diabetes mellitus (T2DM) is caused by the deficiency of insulin secretion and function, accounting for larger than 90% of all DM cases." (PMID 36465705, 2022). "The presence of the ER22/23EK polymorphism results in a healthier metabolic profile, including lower total cholesterol levels, lower fasting insulin levels, increased insulin sensitivity and a lower risk of type 2 diabetes mellitus." (PMID 35054858, 2022). "Insulin is the only substance in the body that causes hypoglycemia, and its secretion state and receptor function is associated with diabetes." (PMID 35885283, 2022). "Insulin-deficient diabetes, or a loss of insulin/IGF-1 action in muscle, reduces complex I-driven mitochondrial respiration and supercomplex assembly through the FoxO-mediated inhibition of complex I subunit." (PMID 35846289, 2022). "The last study, involving 58 853 newly-diagnosed diabetes patients, showed that patients treated with insulin presented a higher risk of osteoporotic fracture amounting to 38%." (PMID 36140292, 2022). "We generated induced pluripotent stem cells (iPSCs) from a patient diagnosed with neonatal diabetes mellitus carrying the INS mutation in the 2nd intron (c.188-31G>A) and engineered isogenic CRISPR/Cas9 mutation-corrected cell lines." (PMID 35955956, 2022). "Diabetes is a chronic disease caused by insufficient insulin secretion or by insulin utilization dysfunction in the body." (PMID 35903672, 2022). "The USP53 genes has a greater involvement in cholestatic liver disease and the IGF2 proteins are widely known as the diabetes associated protein and can control the insulin secretion in β-cells during fasting." (PMID 35277538, 2022). "Earlier diabetes onset and higher insulin dosage (U/kg/day) were associated with a larger body fat % difference between children with T1D and TDC." (PMID 35813369, 2022). "Nonattenders had infrequent self‐blood‐glucose monitoring, were less likely to be insulin pump users, and had higher rates of diabetes‐associated hospitalizations compared to attendees." (PMID 36210875, 2022). "For example, a female aged 55 with one year duration of diabetes and on insulin has an estimated 3-year risk of 6% to develop STDR." (PMID 35898318, 2022). "Low birth weight is associated with reduced expression of insulin signaling proteins in muscle and adipose tissue preceding the development of diabetes." (PMID 36714657, 2022).